RBP7 (retinol binding protein 7)
Description:
Intracellular transport of retinol.
Synonyms: CRABP4; CRBP4; CRBPIV
Tractability: Small molecule: a structure with a bound ligand is known; it has a high-quality binding pocket. PROTAC: its protein half-life has been measured.
Gene: Protein-coding gene on chromosome 1 (9,997,054 to 10,016,021, forward strand). Ensembl gene ENSG00000162444.
Subcellular location: Cytoplasm
Subcellular location (Human Protein Atlas): Cytosol; Nuclear speckles
Gene Ontology:
Molecular function: protein binding; fatty acid binding; lipid binding; retinoid binding
Biological process: fatty acid transport
Cellular component: cytosol; nucleus; cytoplasm
Genetic constraint (gnomAD): Loss-of-function variants: 8 observed, 10.21 expected, observed/expected ratio (o/e) 0.78, 90% interval 0.46 to 1.41. The upper end of that interval is the gene's LOEUF score, 1.41, which puts it in group 5 of 6, group 1 being the genes least tolerant of losing a copy. Missense variants: 112 observed, 124.78 expected, observed/expected ratio (o/e) 0.9, 90% interval 0.77 to 1.05. Synonymous variants: 42 observed, 45.79 expected, observed/expected ratio (o/e) 0.92, 90% interval 0.72 to 1.19.
Homologues: Orthologues: chimpanzee RBP7 (100% identical), pig RBP7 (95% identical), dog RBP7 (94% identical), mouse Rbp7 (90% identical), rat Rbp7 (88% identical), macaque RBP7 (84% identical), zebrafish rbp7b (68% identical), Caenorhabditis elegans lbp-7 (30% identical), Drosophila melanogaster fabp (28% identical), Caenorhabditis elegans lbp-8 (25% identical). Paralogues in human: RBP2 (59% identical), RBP1 (57% identical), RBP5 (49% identical), FABP4 (39% identical), FABP3 (38% identical), FABP7 (37% identical), PMP2 (37% identical), FABP9 (36% identical), FABP12 (35% identical), CRABP1 (34% identical), CRABP2 (34% identical), FABP5 (29% identical), and 3 more.
Diseases named in the same sentence as RBP7 in open-access papers:
RBP7 is named in the same sentence as 35 diseases in open-access papers, as found by Europe PMC text mining. Sharing a sentence is not in itself a finding about the gene and the disease. The quoted sentences say what the papers report.
colon cancer (10 papers, 2019 to 2025). "Aberrant expression of RBP7 has been implicated in several cancers, including breast cancer, bladder urothelial carcinoma and colon cancer, where its expression closely correlates with patients prognosis." (PMID 40636697, 2025). "Gene set enrichment analysis revealed a strong association of RBP7, colon cancer invasion and epithelial mesenchymal transition (EMT)." (PMID 31598160, 2019). "In this study, we explored the expression of RBP7 in colon cancer, analyzed associations with clinicopathological characteristics, and determined its functional relevance for tumor progression." (PMID 31598160, 2019). "Collectively, these data provided additional evidence on the mRNA level that RBP7 expression is associated with advanced tumor stages and colon cancer progression." (PMID 31598160, 2019). "In order to determine the clinical significance of RBP7 expression in colon cancer, we tested for associations with clinicopathological variables and patient follow-up in our collection of 219 cases, which included UICC stages I and II." (PMID 31598160, 2019). "High expression of RBP7 was an independent biomarker of poor cancer specific survival in early and late stage colon cancer, and linked to colon cancer progression." (PMID 31598160, 2019). "Using a collection of 219 stage I and II colon cancer cases with long-term follow-up data, we show that high levels of RBP7 protein expression were strongly linked to poor cancer specific survival." (PMID 31598160, 2019). "Transfection of HCT116 and SW1222 colon cancer cells with RBP7 encoding vector caused strong ectopic expression in both cell lines, when compared to empty control vector." (PMID 31598160, 2019). "RBP7 was closely associated with colon cancer invasion and epithelial-mesenchymal transformation, and ectopic expression of RBP7 enhanced invasion and metastasis of colon cancer." (PMID 36776357, 2022). "RBP7 has been demonstrated as a prognostic biomarker and linked to invasion and EMT in colon cancer but the role of RBP7 in 5-FU chemotherapy resistance remains unknown." (PMID 35784334, 2022). "Collectively, these findings demonstrated significant biomarker potential of RBP7 on protein and mRNA levels that may be useful for risk stratification in patients with colon cancer." (PMID 31598160, 2019). "Additionally, we found that also on the mRNA level, RBP7 was significantly linked with poor outcome in an independent collection of 457 colon cancers from TCGA that included all tumor stages, and also was an independent prognostic biomarker in this case collection." (PMID 31598160, 2019). "RBP7 has been identified as a biomarker with strong prognostic ability in colon cancer in addition to contributing to the malignant phenotype of colon cancer cells." (PMID 36675007, 2023). "Elmasry M's study showed that RBP7 is also a clinical prognostic biomarker and is associated with tumor invasion and EMT of colon cancer." (PMID 35174205, 2022). "High RBP7 expression has been confirmed to be an independent biomarker for poor cancer-specific survival in patients with late- or early-stage colon cancer." (PMID 34421995, 2021). "Therefore, high expression of RBP7 may be particularly useful to identify patients with colon cancer that are at high risk for disease progression, and thus may be candidates for adjuvant chemotherapy and increased clinical attention, despite low clinical stage." (PMID 31598160, 2019). "Ectopic expression of RBP7 increased migration and invasion, which demonstrates a direct functional contribution of RBP7 to the malignant traits of colon cancer cells." (PMID 31598160, 2019). "For further validation, we next tested for clinical correlations of RBP7 mRNA levels using publicly available gene expression data of 457 colon cancer cases from TCGA, 379 of which had information on clinical follow-up." (PMID 31598160, 2019).
colon cancer (continued). "Here, we investigated the potential of RBP7 as a predictive biomarker for patients with colon cancer and determined its functional relevance for tumor progression." (PMID 31598160, 2019). "On the contrary, we demonstrate that RBP7 can be robustly detected by immunohistochemistry in primary colon cancer, and quantified by digital image analysis." (PMID 31598160, 2019). "To learn about the distribution and expression of RBP7 in colon cancer, we examined a collection of 219 tissue specimens." (PMID 31598160, 2019). "Considering these findings, our data provide a new link of retinol metabolism, invasion, and EMT in colon cancer through RBP7." (PMID 31598160, 2019). "To gain insights into the functional role of RBP7 in colon cancer, we conducted Gene Set Enrichment Analyses (GSEA) using the TCGA dataset." (PMID 31598160, 2019). "We analyzed RBP7 protein and mRNA expression in independent tissue collections of colon cancers with recorded follow-up data, including data from TCGA." (PMID 31598160, 2019). "Our findings demonstrate that RBP7 is a strong prognostic biomarker in colon cancer that functionally contributes to the malignant phenotype of colon cancer cells." (PMID 31598160, 2019). "It has also been proposed that RBP7 may serve as a prognostic biomarker in colon cancer and functionally contributes to the malignant phenotype by promoting epithelial-mesenchymal transition (EMT) and tumor invasion." (PMID 40636697, 2025). "Retinol Binding Protein 7 (RBP7) can promote the migration and invasion of colon cancer cells." (PMID 37025597, 2023). "Here, we demonstrate that RBP7 is a prognostic biomarker in colon cancer." (PMID 31598160, 2019). "Finally, due to its link with EMT and cancer invasion, we tested for a functional relevance of RBP7 for invasion and migration of colon cancer cells." (PMID 31598160, 2019). "However, the exact mechanism by which RBP7 drives these malignant traits and affects the transcriptome of colon cancer cells remains to be determined." (PMID 31598160, 2019). "We therefore suggest that RBP7 may serve as a surrogate marker that indicates the overall degree of tumor invasion and EMT within colon cancer, which also may explain its association with poor prognosis." (PMID 31598160, 2019). "Ectopic expression of RBP7 increased migration and invasion of colon cancer cells." (PMID 31598160, 2019). "Moreover, individual markers that indicate or drive EMT in colon cancer showed a significant overexpression in tumors with high RBP7 expression, including ZEB1 (r = 0.27, P < 0.0001) and ZEB2 (r = 0.36, P < 0.0001)." (PMID 31598160, 2019). "This may explain the association of RBP7 with invasion, EMT, and poor prognosis that we observed in colon cancer case collections." (PMID 31598160, 2019). "RBP7 protein was located in the tumor cell nuclei of colon cancers." (PMID 31598160, 2019). "Moreover, a study showed that ectopic expression of RBP7 could enhance the invasion and migration of colon cancer cells." (PMID 34421995, 2021). "In this work, we retrospectively identified four bone metastasis-related genes (INHBB, RBP7, RTN2, and ATOH1) and constructed a gene expression signature model for colon cancer patients by bioinformatic analysis." (PMID 34421995, 2021). "However, in colon cancer, the expression and function of RBP7 yet remains unknown." (PMID 31598160, 2019). "Retinol Binding Protein retinol binding protein 7 (RBP7), a member of the cellular retinol-binding protein (CRBP) family, can independently predict the prognosis of colon cancer patients and promote the migration and invasion of colon cancer cells." (PMID 38662077, 2024). "Further study also is required to elaborate whether therapeutic interference with retinol metabolism and RBP7 may be a strategy to target invasion, EMT, and colon cancer progression." (PMID 31598160, 2019).
colon cancer (continued). "RBP7 is a member of the cellular retinol-binding protein (CRBP) family and previous data suggested a link between CRBPs and the malignant transformation of colon cancer cells." (PMID 31598160, 2019).
breast carcinoma (7 papers, 2018 to 2025). "We found that RBP7 shows patterns linked to better outcomes in several cancers, including breast cancer." (PMID 41301068, 2025). "Low RBP7 expression has been associated with poorer overall survival and disease-free survival in breast cancer patients." (PMID 41301068, 2025). "In conclusion, this study provides the first evidence that RBP7 downregulation in breast cancer is associated with promoter methylation." (PMID 36276273, 2022). "Survival analysis with 4 different databases showed that low expression of RBP7 was significantly associated with poor OS in breast cancer patients." (PMID 36276273, 2022). "Based on the results above, we conclude that RBP7 may be a tumor suppressor gene and that high expression of RBP7 is associated with a good prognosis for ER+ breast cancer patients." (PMID 36276273, 2022). "Kaplan–Meier survival analysis was performed with the GSE20685 and GSE42568 datasets from the GEO database to evaluate the prognostic value of RBP7 in breast cancer, which showed that lower expression of RBP7 was associated with a poorer prognosis in breast cancer." (PMID 36276273, 2022). "The loss of RBP7 expression has been shown to promote tumor progression by affecting the PPAR and PI3K/AKT signaling pathways in estrogen receptor-positive (ER+) breast cancer." (PMID 40636697, 2025). "It was shown that RBP7 is significantly downregulated in hormone receptor-positive (HR+) breast cancer tissues compared to normal tissues, and its low expression correlates with poor overall survival (OS) and higher tumor T-stage and Ki67 score." (PMID 40427160, 2025). "Although previous researchers had investigated RBP7 in breast cancers, our study newly explored the role of RBPs across all cancer types and highlighted the role of RBP4 and RBP7 in TNBC." (PMID 41301068, 2025). "Cox analysis identified RBP4 as a protective gene in kidney renal papillary cell carcinoma (KIRP), liver hepatocellular carcinoma (LIHC), and mesothelioma (MESO), while RBP7 exhibited protective effects in breast cancer (BRCA) and uveal melanoma (UVM)." (PMID 41301068, 2025). "Mechanistically, RBP7 induced G0/G1 cell cycle arrest and reduced fatty acid levels in HR+ breast cancer cells and xenograft models." (PMID 40427160, 2025). "Next, we validated the expression and prognostic significance of RBP7 using tissue microarray and immunohistochemistry in pathological specimens from 47 breast cancer patients." (PMID 41301068, 2025). "Recent research has highlighted RBP7’s potential role in breast cancer, drawing attention to its influence on tumor biology and patient prognosis." (PMID 41301068, 2025). "Further research is needed to determine the role of RBP7 in breast cancer biology and its potential as a therapeutic target." (PMID 38553715, 2024). "A study based on bioinformatics analysis predicted that RBP7 silencing by methylation promoted breast cancer through the PPAR and PI3K/AKT pathways." (PMID 38553715, 2024). "We subsequently utilized the transcriptomic sequencing data in the GEPIA database to assess the prognostic value of RBP7 in breast cancer and found that a high level of expression of RBP7 was favorable to the prognosis of breast cancer." (PMID 36276273, 2022). "We utilized the MethSurv database to identify the methylation sites of RBP7 in breast cancer and found 4 probes, namely, cg20413202, cg03406535, cg10796749, and cg14202757, located in TSS1500-N_Shore with high methylation." (PMID 36276273, 2022). "We found that RBP7 was overexpressed in liver cancer and lymphoma, but decreased expression of RBP7 was found in brain and CNS cancer, breast cancer, esophageal cancer, head and neck cancer, leukemia, and ovarian cancer." (PMID 36276273, 2022). "The TCGA database results revealed that the mRNA expression level of RBP7 was lower in breast cancer than in normal tissues, which was further validated by the GSE37751 dataset from the GEO database." (PMID 36276273, 2022).
breast carcinoma (continued). "We used the TISCH database to analyze the expression of RBP7 in different cells from breast cancer tissues." (PMID 36276273, 2022). "Our results demonstrated that the gene expression of RBP7 in breast cancer was significantly lower than that in normal controls." (PMID 36276273, 2022). "A heat map of the gene module analysis depicts the expression of RBP7 in different cell types of breast cancer datasets, in which endothelial and epithelial cells are characterized by high expression of RBP7." (PMID 36276273, 2022). "Bioinformatics analysis with the TCGA and CPTAC databases revealed that the mRNA and protein expression levels of RBP7 in normal were higher compared to breast cancer tissues." (PMID 36276273, 2022). "It is reasonable to propose that upregulation of RBP7 by E2 leads to a good prognosis in ER+ breast cancer." (PMID 36276273, 2022). "To further explore the mechanism of the differential expression of RBP7 in breast cancer and normal tissues, we performed hierarchical clustering analysis of RBP7 mRNA expression related to DNA methylation by using the UCSC Cancer Genomics Browser." (PMID 36276273, 2022). "Survival analysis displayed that the lower expression of RBP7, the worse the prognosis in ER-positive (ER+) breast cancer patients." (PMID 36276273, 2022). "The study aims to illustrate the prognostic value and the potential regulatory mechanisms of RBP7 expression in breast cancer." (PMID 36276273, 2022). "Consistently, we found that most of the median beta values of different clinical stages were also above 0.6, suggesting that promoter methylation leads to the inhibition of RBP7 gene transcription in breast cancer." (PMID 36276273, 2022). "In this study, we utilized various databases to explore the expression, prognosis, cellular localization, coexpression network, DNA methylation, and function of RBP7 in breast cancer." (PMID 36276273, 2022). "In this study, we first analyzed the differential expression of RBP7 in breast cancer and normal tissues and evaluated the prognostic value of RBP7 by using data from the TCGA and GEO databases." (PMID 36276273, 2022). "Deep bioinformatics analysis of RBP7-related pathways reveals some vital information for the regulatory mechanism in ER+ breast cancer." (PMID 36276273, 2022). "Next, we performed methylation analysis with the Methsurv database and found that 4 methylation probes, namely, cg20413202, cg03406535, cg10796749, and cg14202757, in the promoter of RBP7 were highly methylated in breast cancer." (PMID 36276273, 2022). "In summary, we identified RBP7 as a novel biomarker that is helpful for the prognosis of ER+ breast cancer patients." (PMID 36276273, 2022). "Then, we utilized the immunohistochemistry (IHC) data detected by the HPA-034749 antibody from the HPA database to determine the protein expression of RBP7 in breast cancer and normal tissues." (PMID 36276273, 2022). "Genomic analysis showed that low expression of RBP7 correlates with its promoter hypermethylation in breast cancer." (PMID 36276273, 2022). "To further illuminate the role of RBP7 in the progression of breast cancer, we analyzed the expression and prognosis of RBP7 in different molecular subtypes of breast cancer." (PMID 36276273, 2022). "Promoter methylation of RBP7 is involved in its gene silencing in breast cancer, thus regulating the occurrence and development of ER+ breast cancer through the PPAR and PI3K/AKT pathways." (PMID 36276273, 2022). "RBP7 expression was higher in PR-positive breast cancer patients than in PR-negative patients, whereas RBP7 expression was higher in HER2-negative breast cancer patients than in HER2-positive patients." (PMID 36276273, 2022). "Subsequently, we used the SMART App to verify the Spearman correlation between gene expression and DNA methylation of the probes of RBP7 in breast cancer." (PMID 36276273, 2022).